TNF (tumor necrosis factor)
Diseases named in the same sentence as TNF in open-access papers (continued):
Sharing a sentence is not in itself a finding about the gene and the disease.
Insulin resistance (continued). "Therefore, inhibiting NF-κB activation and reducing the expression of TNF-α and IRS-1Ser307 phosphorylation were of great significance for the prevention and treatment of NAFLD insulin resistance." (PMID 28630632, 2017). "Insulin resistance has been considered an important mechanism for the muscle wasting in cachexia as it increases proteolysis by increasing the expression of UPP components, and TNFα is responsible for this." (PMID 29081600, 2017). "In conclusion, in this study, CRP, IL-6, and TNF-α were significantly elevated in obese Egyptian type 2 diabetics and were positively correlated with insulin resistance, non-HDL and triglycerides." (PMID 29099041, 2017). "RBPP-P attenuated the contents of TNF-α and IL-6 in HFD-fed mice adipose tissues, indicating that it decreased fat mass and improved insulin resistance, which may be related to the regulation of inflammation." (PMID 28452943, 2017). "Chronic low-grade inflammation is characterised by the increased production of inflammatory adipose tissue-specific secretory proteins (adipokines), such as tumor necrosis factor (TNF) α and interleukin (IL) 6, contributing to glucose intolerance and insulin resistance." (PMID 28870184, 2017). "Tumor necrosis factor-α is a macrophage-derived inflammatory factor; it alters insulin signaling in cultured cells and in vivo, and it has been reported that chronic exposure of cells or whole animals to TNF-α induces insulin resistance." (PMID 28178209, 2017). "Besides, correlations between TBS and indexes of insulin resistance (HOMA) and insulin sensitivity (QUICKI) were also found after TNF-α blockade." (PMID 27293954, 2016). "TNF attenuates the insulin-stimulated tyrosine phosphorylation of insulin receptor (IR) and insulin receptor substrate 1 (IRS1) in adipose tissue and muscle, resulting in the occurrence of insulin resistance." (PMID 28025491, 2016). "A study demonstrating the anti-inflammatory properties of n-3 PUFA via suppression of toll-like receptor 4 (TLR4) activation in muscle reported improvements in inflammatory markers (TNFα, CRP, IL-6) and insulin resistance as measured from oral glucose and insulin tolerance tests (OGTT and ITT)." (PMID 27258299, 2016). "Thus, the expression of inflammation tumor necrosis factor-α (TNF-α) and IL-6 amplifies insulin resistance in the adipose tissues of HFD animals." (PMID 28231175, 2016). "Moreover, after 12 weeks of VNS treatment, VNS significantly reduced both cardiac and serum TNF-α levels compared with the sham group, suggesting that VNS attenuated cardiac inflammation and oxidative stress in obese-insulin resistance." (PMID 26830020, 2016). "Since PTEN inhibition restores vascular insulin sensitivity, decreased by TNF-α and HFD, PTEN may be considered a major contributor to TNF-α-induced insulin resistance." (PMID 27562094, 2016). "Nevertheless, in our series of nondiabetic patients with moderate-to severe- psoriasis, we observed a significant correlation between insulin resistance (negative) and insulin sensitivity (positive) after 6 months of anti-TNF-α therapy." (PMID 27293954, 2016). "In addition, TNF-α increases PTEN phosphorylation in C2C12 cells, a mouse myoblast cell line, leading to insulin resistance." (PMID 27562094, 2016). "It is well established that TNF-α can activate JNK and induce insulin resistance." (PMID 27841334, 2016). "Physiological hyperglycemia generates increased levels of ROS from mononuclear cells, which then activate the release of TNF-α and increase inflammatory transcription factor NF-kappa B. As a result, the concentrations of TNF-α, a known mediator of insulin resistance, are further increased." (PMID 27423183, 2016). "Similarly to TNFα, both IL-6 and MCP-1 are critically involved in insulin resistance and chronic inflammation." (PMID 25685071, 2015).
Insulin resistance (continued). "In other words, elevation of the serum levels of TNF-α and IL-12 in our study population seems to be preferentially related to the fat mass gain rather than the occurrence of obstructive sleep apnea and insulin resistance." (PMID 25944984, 2015). "Moreover, increased activation of inflammatory pathways (i.e., p38 MAPK and NF-κB) in presence of insulin resistance is evidenced together with elevated protein mass of IL-6, ICAM and COX-2, as well as of the mRNA levels of TNF-α." (PMID 26376914, 2015). "TNF-α leads to insulin resistance also in non-adipose tissues such as liver and muscle and promote FA mobilization from adipose tissue to oxidative tissues." (PMID 26580649, 2015). "Interestingly, in the livers of rats maintained on the soybean diet, the expression of TNFα was correlated with the HOMA-IR index, confirming the role of this cytokine in the development of hepatic insulin resistance." (PMID 25892856, 2015). "Although this diet induced insulin resistance and increased liver oxidative stress, proinflammatory mediators such as TNF-α, IL-6, and NF-κB were not enhanced." (PMID 26064924, 2015). "TNF-α or IL-6 downregulated insulin-stimulated glucose uptake and consumption in three types of cell lines, and casein injection decreased glucose and insulin tolerance in C57BL/6J mice, indicating that the inflammatory stress promoted insulin resistance." (PMID 26449763, 2015). "Our data suggest a possible positive role for IL-6 in suppressing the level of TNF-α and MCP-1, in maintaining adipose tissue homeostasis and in preventing the consequences of high proinflammatory cytokine levels, as insulin resistance and other elements of the metabolic syndrome." (PMID 25611388, 2015). "Therefore, we provide a novel finding that miR-15b and miR-16 play a role in preventing insulin resistance in REC cultured in high glucose, via reduced activation of TNFα and SOCS3 pathways and increased IGFBP-3 levels." (PMID 25888955, 2015). "They showed that PGRN expression was induced by TNF-α or dexamethasone and decreased with differentiation of adipocytes, and ablation of PGRN prevented mice from high fat diet-induced insulin resistance and blocked elevation of an inflammatory cytokine, IL-6, in adipose tissue." (PMID 26106251, 2015). "Furthermore, the homeostasis model assessment of insulin resistance (HOMA-IR) index and serum proinflammatory cytokine levels (TNF-α and IL-6) involved in dyslipidaemia was markedly improved." (PMID 26264374, 2015). "Pentoxifylline therapy reduced proteinuria and improved glucose control and insulin resistance without significant change of serum TNF-α in patients with type 2 diabetic nephropathy." (PMID 26300986, 2015). "Attempts to reverse insulin resistance with an injection of anti-TNF binding proteins finally fail, indirectly supporting the speculation that TNF-α functions locally at AT via a paracrine or autocrine fashion." (PMID 26339623, 2015). "In addition to TNFα actions on IRS-1, TNFα also can activate other proteins known to be involved in insulin resistance, namely suppressor of cytokine signaling 3 (SOCS3)." (PMID 25874611, 2015). "In addition, increased levels of TNFα and SOCS3 lead to enhanced IRS-1 phosphorylation on serine 307, elevated IR (Tyr960), and decreased phosphorylation of IR (Tyr1150/1151), leading to insulin resistance and increased apoptosis." (PMID 25888955, 2015). "Our findings showed that CLE effectively decreased the production of inflammatory mediators, such as IL-6, TNF-α, and FFA in db/db mice, which could be due to decreased HOMA-IR and insulin, constantly improving insulin resistance in target tissues." (PMID 25889508, 2015). "Additionally, diabetes is associated with high levels of blood cytokines including IL-1β, IL-6, IL-12, IL-17, IL-18, TNF-α and IFN-γ, which mediate the physiological adaption of insulin production and insulin resistance." (PMID 26684748, 2015).
Insulin resistance (continued). "In conclusion, MI induces myocardial insulin resistance (without systemic insulin resistance) mediated partly by ischemia-induced myocardial TNF-α overproduction and promotes the development of HF." (PMID 26659007, 2015). "Thus, TNF-α and SOCS3 require an active serine 307 phosphorylation site on IRS-1 to bring about insulin resistance." (PMID 25352752, 2014). "TNFα and IGFBP-3 may both be involved in insulin resistance, as we previously demonstrated that TNFα is key to activation of an insulin resistance phenotype in REC, noted by increased IRS-1Ser307 and IRTyr960, with increased apoptosis of REC." (PMID 25073020, 2014). "Thus, pro-inflammatory cytokines including TNF-α have been described to decrease circulatory levels of APN and promote chronic inflammation and insulin resistance." (PMID 24836538, 2014). "Although it is known that TNF-α stimulates the synthesis of CRP in the liver, correlation coefficient between circulating levels of TNF-α and CRP is 0.173 in the present study and 0.27 in a large, multiethnic population of the Insulin Resistance Atherosclerosis Study." (PMID 25105150, 2014). "Treatment with anti-TNF-α in humans has so far not shown any results indicating a beneficial effect on insulin resistance or GSIS." (PMID 24692847, 2014). "TNF-α also promotes ceramide accrual by activating sphingomyelinase, an enzyme that catalyzes the hydrolysis of sphingomyelin to ceramide, and ceramide mediates TNF-α-induced insulin resistance in adipocytes." (PMID 24733068, 2014). "However, an intravenous treatment with 600mg of ALA for two weeks in obese patients with glucose intolerance resulted in improvement of insulin resistance, decreased levels of free fatty acids, LDL-cholesterol as well oxidized LDL, TNF α and IL-6." (PMID 25104975, 2014). "Our results support previous human studies suggesting that TNF-α plays a role in development of type 2 diabetes mainly by inducing insulin resistance and not by impairment of the insulin secretion by the β-cell." (PMID 24692847, 2014). "Moreover, IL-6 and TNF-α increase expression of SOCS in the liver which is involved in increased hepatic SREBP-1c expression and insulin resistance." (PMID 24733068, 2014). "A larger study compared probiotics and fructooligosaccharides to life style changes in NAFLD with the probiotics arm significantly reducing TNF-α, CRP, serum AST levels, homeostasis model assessment of insulin resistance, serum endotoxin, steatosis, and the NASH activity index." (PMID 25436233, 2014). "The circulating levels of adipocytokines, such as tumor necrosis factor-α (TNF-α) and interleukin 6, which raise insulin resistance, are higher in obese and nonobese women with PCOS than those in weight matched non-PCOS control women." (PMID 24079935, 2013). "Beside its direct negative interference with the insulin signaling pathway, TNF-α also indirectly induces insulin resistance by altering adipocyte differentiation and adipocyte lipid metabolism." (PMID 24455420, 2013). "Our present study revealed that Lr263 administration markedly suppressed the increased TNF-α and IL-6 production by adipose tissue in HFD rats, suggesting that Lr263 ameliorated insulin resistance through reducing oxidative stress as well as proinflammatory cytokines production." (PMID 23590862, 2013). "Conclusively, TNF-α role in modulating insulin resistance with no doubt varies from species to species and depends on animal models adopted for particular study." (PMID 23762871, 2013). "The general mechanisms of IL-18 in the context of insulin resistance involve lineal effects of IL-18 on insulin signaling with or without tumor necrosis factor-α (TNF-α) stimulation in tissues and a secondary response of IL-18 to insulin resistance." (PMID 24282409, 2013).
Insulin resistance (continued). "A recent cohort study on nondiabetic patients with insulin resistance has shown concomitant decrease in TNF-α level accompanied by an improvement in insulin resistance after administration of rosiglitazone." (PMID 23762871, 2013). "Finally, resistin has been demonstrated to stimulate the secretion of several inflammatory factors (e.g., TNF-α, IL-6, IL-8, and MCP-1) known to play a role in the induction of insulin resistance." (PMID 24455420, 2013). "Lack of any correlation between leptin/TNF-α and insulin resistance in our south Asian population was an unexpected finding." (PMID 23671875, 2013). "In contrast, obese mice lacking either TNF-α or its receptors are protected from developing insulin resistance." (PMID 24349514, 2013). "Similarly, IL-6 and TNF-α have been shown to suppress insulin signaling and GLUT-4 receptor expression in skeletal muscle, both of which result in insulin resistance." (PMID 23826335, 2013). "This indicates that TNFα may be a crucial mediator of inflammation in WAT and whole-body insulin resistance of Crif1f/+,Fabp4 mice." (PMID 23516375, 2013). "It has been shown that TNF-α expression is increased in the adipose tissue of obese individuals, that its level is correlated with adiposity and numerous studies have highlighted TNF-α involvement in the etiology of insulin resistance." (PMID 23824685, 2013). "In rodents TNF-α is overexpressed in adipose tissue from obese animals, and obese mice lacking either TNF-α or its receptor show protection against the development of insulin resistance." (PMID 24455420, 2013). "White adipose tissue (WAT), represented herein by epidydimal fat content, participates in the induction of whole-body insulin resistance, partly by the macrophage infiltration-induced chronic inflammation of WAT and/or the release of TNF-α, which is highly expressed in WAT." (PMID 23300941, 2013). "When adjusted for insulin resistance (HOMA-IR) or adipocytokines (leptin, hsCRP, TNF-α) the β coefficient for BMI was attenuated in each instance >50%; consistent with both insulin resistance and inflammation mediating the association of BMI with endothelial function." (PMID 24164965, 2013). "TNFα was found to phosphorylate IRS-1 and IRS-2 and therefore interfere in the signaling of the tyrosine kinase of the IR which might also contribute to insulin resistance." (PMID 23819063, 2013). "In one rodent model, obese mice lacking either TNF-α or its receptors showed protection against developing insulin resistance." (PMID 23762871, 2013). "Non-fasting blood glucose level, serum insulin level, insulin resistance index, serum tumour necrosis factor-α (TNF-α) and serum C-reactive protein (CRP) were determined." (PMID 23717483, 2013). "It has also been reported that tumor necrosis factor-α induces insulin resistance, and systemic inflammation has been identified as a novel predictor of incident diabetes." (PMID 23940623, 2013). "In vivo release of interleukin-6 (IL-6), linked closely to hs-CRP pathway, but not tumor necrosis factor-α (TNF-α), which is related to insulin resistance, has been reported in human subcutaneous adipose tissue (SAT)." (PMID 23326306, 2013). "An increase of IL-6 (p = 0.015) and TNF (from 49.7 to 53 pg/mL), and a decrease of plasma APO (7658–5152 ng/ml, respectively) were noted after hemihepatectomy, the surgery also resulted in exacerbation of insulin resistance evaluated by HOMA index (p = 0.007)." (PMID 22829443, 2013). "Anti-TNF therapy resulted in significant improvement in HOMA-IR (P < 0.001), QUICKI (P < 0.001), and HOMA-B (P = 0.001) only in RA patients with high baseline insulin resistance." (PMID 22691241, 2012). "Tumor necrosis factor (TNF), a pro-inflammatory cytokine with a major pathogenetic role in RA, may promote insulin resistance by inducing Ser312 phosphorylation (p-Ser312) of insulin receptor substrate (IRS)-1 and downregulating phosphorylated (p-)AKT." (PMID 22691241, 2012).
Insulin resistance (continued). "Both IL-6 and TNF may inhibit the transcription of IRS-1 and glucose transporter (GLUT)-4 genes, thus reducing glucose transport and enhancing insulin resistance in obese patients." (PMID 22691241, 2012). "As insulin resistance in new onset diabetic NOD mice is accompanied by defective in vivo insulin signaling in tissues that are targeted for glucose disposal, we examined the effects of anti-TNF-α upon insulin signaling in fat of new onset diabetic NOD mice." (PMID 22606220, 2012). "ROS activate the nuclear factor kappa-light-chain-enhancer of activated B cells (NFkB), which are able to stimulate inflammatory factor synthesis (i.e. Tumor Necrosis Factor-α [TNF-α]),that is a mediator of insulin resistance, and is highly expressed in PCOS patients." (PMID 23843832, 2012). "Furthermore, TNF-α can stimulate the production of other cytokines and chemokines, such as IL-6 and Monocyte Chemoattractant Protein 1 (MCP1), which can induce insulin resistance." (PMID 22816003, 2012). "We postulate that FWFE can alleviate insulin resistance via inhibiting the intracellular JNK inflammatory signaling cascades, restoring the PI3K-Akt/PKB insulin signaling pathway, and then enhancing glucose uptake in TNF-α-treated FL83B mouse hepatocytes." (PMID 22942720, 2012). "In myeloid-specific Iκκ-β (an activator of NF-κB)-deficient mice, a decrease in proinflammatory cytokine production (IL-1β, IL-6, TNF-α, and MCP-1) and the inhibition of NF-κB activation has been reported, avoiding, in this way, the development of insulin resistance." (PMID 23326021, 2012). "IL1-β and TNFα induce IRS-2 phosphorylation, which leads to insulin resistance, followed by the apoptotic death of β cells; the inhibition of cytokines by AS101 may contribute to β cell preservation." (PMID 22761194, 2012). "Therefore, the activation of these signaling pathways induces the production of more IL-1β, TNF-α, and MCP-1 and high levels of iNOS expression, contributing to insulin resistance in different tissues." (PMID 23326021, 2012). "Physiological hyperglycemia generates increased levels of ROS from mononuclear cells, which then activate the release of TNF-alpha and increase inflammatory transcription factor NF-kappa B. As a result, concentrations of TNF-alpha, a known mediator of insulin resistance, are further increased." (PMID 22748101, 2012). "TNF-α selectively stimulates the expression of a key component of its own signaling pathway, Mitogen-activated protein 4 kinase isoform 4 (Map4k4), through a TNFR1-dependent mechanism to induce insulin resistance in adipose tissue." (PMID 22816003, 2012). "In moderate dose endotoxemia, we observed strong induction of subcutaneous adipose TNF and IL-6 as well as MCP-1, which is known to recruit CCR-2 expressing monocytes, increase inflammatory-M1 adipose tissue macrophage (ATM) and promote insulin resistance." (PMID 22709547, 2012). "Assessments included body mass index (BMI), insulin sensitivity (Homeostasis Model Assessment of insulin resistance, HOMA and the Quantitative Insulin sensitivity Check Index, QUICKI), and RA disease characteristics before and following six months of anti-TNFα treatment." (PMID 22765047, 2012). "FTox-G50-induced insulin resistance in skeletal muscle was not abolished by anti-TNF-α treatment and Map4k4 expression was not activated in skeletal muscle of mice injected with FTox-G50." (PMID 22816003, 2012). "Anti-TNFα therapy, through controlling inflammation, seems to improve insulin sensitivity in normal-weight RA patients with insulin resistance, but is not sufficient to achieving the same beneficial effect in obese RA patients with insulin resistance." (PMID 22765047, 2012). "Of note, elevated levels of TNFα, IL-1β, IL-6 and IL-10 mRNA in MO with high insulin resistance degree were not statistically different from the levels found in T2D-MO." (PMID 23110196, 2012).